TECPR2 (tectonin beta-propeller repeat containing 2)
Description:
Probably plays a role as positive regulator of autophagy.
Synonyms: KIAA0329; HSAN9; SPG49
Tractability: PROTAC: its protein half-life has been measured.
Gene: Protein-coding gene on chromosome 14 (102,362,941 to 102,502,477, forward strand). Ensembl gene ENSG00000196663.
Subcellular location (Human Protein Atlas): Nucleoplasm; Centrosome; Nucleoli
Gene Ontology:
Molecular function: protein binding
Genetic constraint (gnomAD): Loss-of-function variants: 67 observed, 135.34 expected, observed/expected ratio (o/e) 0.5, 90% interval 0.41 to 0.61. The upper end of that interval is the gene's LOEUF score, 0.61, which puts it in group 2 of 6, group 1 being the genes least tolerant of losing a copy. Missense variants: 1,513 observed, 1,783.4 expected, observed/expected ratio (o/e) 0.85, 90% interval 0.81 to 0.88. Synonymous variants: 728 observed, 735.03 expected, observed/expected ratio (o/e) 0.99, 90% interval 0.93 to 1.05.
Homologues: Orthologues: chimpanzee TECPR2 (99% identical), macaque TECPR2 (93% identical), dog TECPR2 (86% identical), rabbit TECPR2 (85% identical), mouse Tecpr2 (83% identical), pig TECPR2 (81% identical), rat Tecpr2 (79% identical), guinea pig TECPR2 (76% identical), tropical clawed frog tecpr2 (61% identical), zebrafish tecpr2 (54% identical), Caenorhabditis elegans W09G3.6 (16% identical), Drosophila melanogaster CG11141 (14% identical). Paralogues in human: HPS5 (15% identical).
Diseases named in the same sentence as TECPR2 in open-access papers:
TECPR2 is named in the same sentence as 17 diseases in open-access papers, as found by Europe PMC text mining. Sharing a sentence is not in itself a finding about the gene and the disease. The quoted sentences say what the papers report.
Spastic paraplegia (4 papers, 2016 to 2025). Complete loss of the ability to move the lower limbs accompanied by spasticity of the lower limbs. "For example, SPG49 is another form of complicated spastic paraplegia caused by mutation of the TECPR2 gene encoding an LC3B-interacting protein." (PMID 29698489, 2018). "Autosomal-recessive spastic paraplegia 49 due to homozygosity for a TECPR2 founder mutation in Jewish Bukharian families is a complex multisystem disorder characterized by distinct dysmorphic features, severe central apneas, progressive intellectual impairment, spastic paraplegia and ataxia." (PMID 34130600, 2022). "Several monogenic disorders may be categorized as both defects in autophagy and vesicular trafficking, for instance RAB7A‐related neuropathy or TECPR2‐related spastic paraplegia." (PMID 39420677, 2025). "At the time of its introduction in 2016, six conditions (EPG5‐related Vici syndrome, WDR45‐related BPAN, SNX14‐related ataxia as well as SPG11‐, ZFYVE26‐, and TECPR2‐related spastic paraplegia) were included with the concept of congenital disorders of autophagy." (PMID 39420677, 2025).
Intellectual disability (3 papers, 2023 to 2026). "Mutations in TECPR2 cause hereditary spastic paraplegia type 49 (SPG49), a neurodegenerative disorder of intellectual disability, chronic respiratory disease and decreased pain sensitivity." (PMID 37409490, 2023). "TECPR2‐related hereditary sensory and autonomic neuropathy with intellectual disability is characterized by developmental delay, microcephaly, and subsequent intellectual disability, behavioral abnormalities." (PMID 39932116, 2025).
and autonomic neuropathy (2 papers, 2023 to 2026). "Recent reports of spatial proteomics in TECPR2-related hereditary sensory and autonomic neuropathy indeed also implicated these vesicular trafficking pathways, specifically ER-to-Golgi transport via coated vesicles." (PMID 37895210, 2023). "A recent study identified TECPR2-related hereditary sensory and autonomic neuropathy in two Palestinian siblings, presenting with acute encephalopathy and severe multi-organ dysfunction, expanding the clinical and genetic spectrum of TECPR2 mutations." (PMID 41277110, 2026).
Anxiety (1 paper, 2025). Intense feelings of nervousness, tension, or panic often arise in response to interpersonal stresses. "In response to a novel, mildly stressful environment, Tecpr2 ki/ki mice spent more time moving in the central aversive zone of the open field, indicative of decreased anxiety-related behavior." (PMID 41173829, 2025).
hereditary sensory and autonomic neuropathy (1 paper, 2017). An instance of sensory peripheral neuropathy that is caused by an inherited modification of the individual's genome. "Mutations in TECPR2 leading to the translation of a truncated and unstable version of TECPR2 cause a form of HSP and hereditary sensory and autonomic neuropathy (HSAN-III)." (PMID 28553203, 2017).
sarcopenia (1 paper, 2024). Progressive decline in muscle mass due to aging which results in decreased functional capacity of muscles. "Consistently across the three outcomes, RXRA, MDM1, RBL2, KCNJ2, and ADHFE1 were identified as risk factors, while NMB, TECPR2, MGAT3, ECHDC2, and GINM1 were identified as protective factors, all with potential as biomarkers for sarcopenia progression." (PMID 39409102, 2024).
neurodegenerative disease (1 paper, 2025). A disorder of the central nervous system characterized by gradual and progressive loss of neural tissue and neurologic function. "While mRNA expression of Tecpr2 was robustly reduced as expected from the absence of Tecpr2 at the protein level, numerous microglia and astrocytes genes associated with neurodegenerative disease transcriptomic signatures were significantly upregulated." (PMID 41173829, 2025).
neurological disorder (1 paper, 2023). "Hereditary sensory and autonomic neuropathy 9 (HSAN9) is a rare fatal neurological disease caused by mis- and nonsense mutations in the gene encoding for Tectonin β-propeller repeat containing protein 2 (TECPR2)." (PMID 36797266, 2023). "For the neurological disorder-associated proteins SPG20 and NEK9 as well as the co-chaperone BAG2, these alterations were confirmed by immunoblotting for biotinylated proximity partners of APEX2-SEC13 and -SEC16A in TECPR2 WT and MUT cells." (PMID 36797266, 2023).
TECPR2 also shares sentences with these, for which no sentence is quoted: hereditary spastic paraplegia (3 papers); neuropathy (2); Vici syndrome (2); Acute encephalopathy (1); Cerebellar atrophy (1); hereditary spastic paraplegia type 49 (1); intellectual disability syndrome (1); neuroaxonal dystrophy (1); peripheral nerve lesion (1).